TWIST1 (twist family bHLH transcription factor 1)
Diseases named in the same sentence as TWIST1 in open-access papers (continued):
Sharing a sentence is not in itself a finding about the gene and the disease.
breast carcinoma (continued). "We first overexpressed USP29 in luminal breast cancer cell MCF‐7, in which the expression of USP29 and TWIST1 is much lower than TNBC cells." (PMID 36782089, 2023). "Since TWIST1 critically contributes to breast CSC‐like properties, we also evaluated the function of CDK1 in CSC properties of breast cancer cells." (PMID 36782089, 2023). "To fully explore the interplay between USP13 and Twist1, we examined the role of USP13 in inducing breast cancer cell migration and invasion through Twist1." (PMID 36732432, 2023). "TQ has also been reported to increase the methylation level and decrease the mRNA level of the TWIST1 oncogene, which resulted in growth inhibition of SiHa and CaSki cervical cancer cells, and BT549 human breast cancer cells." (PMID 37375831, 2023). "In normal breast epithelial and breast cancer cells, both IKK-β and NF-κB p65 were required for TNF-α-induced Twist1 expression, suggesting the involvement of canonical NF-κB signaling in EMT in these cells." (PMID 37611445, 2023). "Hypoxia-induced lncRNA RP11-390F4.3, Wnt/β-catenin signaling, and IKK-2/IκBα/NF-κB pathway in breast cancer can regulate multiple EMT regulators such as Snail, Twist1, and ZEB1/2 to promote tumor metastasis." (PMID 35457185, 2022). "Hsa-circ-0061825 (circ-TFF1) contributes to BC via targeting miR-326/TFF1, and circNOT2 can prevent breast cancer invasion, migration and EMT by regulating twist family BHLH transcription factor via targeting miR-409-3p/Twist1." (PMID 35806027, 2022). "It has been shown that Snail can transiently repress the transcription of Twist1 in response to TGFβ stimuli, which is followed by Snail degradation, Twist1 reexpression, and consequent EMT as well as tumor metastasis in breast cancer." (PMID 35601657, 2022). "The clinically available AKT1 inhibitor, MK-2206, can stabilize TWIST1 and enhance EMT and metastasis in breast cancer cells." (PMID 36115849, 2022). "For example, the loss of G3BP2 has been shown to promote nuclear translocation of TWIST1 with increasing matrix stiffness to drive epithelial-mesenchymal transition (EMT) tumor invasion and metastasis in breast cancer." (PMID 34782720, 2022). "GCs can promote metastasis of certain type of breast cancer cells, and TTP inhibits the migration of cancer cells by suppressing the expression of Twist1 and Snail1." (PMID 36430156, 2022). "A mechanistic link between TWIST1, ETM, and metastasis has been established in human breast cancers." (PMID 35745656, 2022). "It has also been reported that the increased expression of TWIST1 induced the expression of stemness markers and enhanced self-renewal in human head and neck squamous cell carcinoma, ESCC, as well as cervical and breast cancers." (PMID 36553636, 2022). "We predict transcription factors known to be involved in cancer as well as novel candidates to drive hypo-methylated regions such as FOXA1 and GATA3 in breast cancer, FOXA1 and TWIST1 in prostate cancer and NFE2L2 in lung cancer." (PMID 35331302, 2022). "Significant downregulation of the miR-200 family, which consists of miR-141, miR-200a, miR-200b, miR-200c, and miR-429, regulates the expressions of mesenchymal markers ZEB1, ZEB2, TWIST1, TWIST2, Snai1, and Snai2 and promotes EMT in breast cancer." (PMID 37533517, 2022). "miR-381-3p inhibits breast cancer progression and EMT progression by targeting Sox4 and Twist1 expression and downregulating Smad protein, which is downstream of TGF-β." (PMID 35805066, 2022). "In the current study, we found that SPOP destabilizes TWIST1 through the ubiquitin proteasomal pathway, thereby inhibiting EMT and breast cancer metastasis in vitro and in vivo." (PMID 36115849, 2022). "In breast cancer, AEG-1 promoted CSC expansion by increasing the transcription of TWIST1, a transcription factor critical for metastasis and stemness." (PMID 33918653, 2021).
breast carcinoma (continued). "Activated HIF1α or HIF2α directly or indirectly regulate SNAI1, TWIST1 and ZEB1 expression which fosters stemness and metastasis formation in bladder, ovarian, gastric and breast cancer." (PMID 34459003, 2021). "Upstream of TWIST1, Metadherin (MTDH) was shown to epigenetically activate TWIST1 to promote stem-like traits in breast cancer." (PMID 34277708, 2021). "By regulation, posttranslational modification of Twist proteins can impact their functions both positively and negatively; for instance, phosphorylation of Twist1 by MAP enhances its stability, promoting invasiveness and EMT in breast cancer cells." (PMID 34868979, 2021). "miR-381-3p inhibits breast cancer progression and EMT by regulating the TGF-β signaling via targeting Sox4 and Twist1." (PMID 34362391, 2021). "Our observation suggests that miR-381-3p inhibits breast cancer progression and EMT by regulating the TGF-β signaling via targeting Sox4 and Twist1." (PMID 34362391, 2021). "Overexpression of SNAI1, TWIST1, and ZEB1 in breast cancer is sufficient to increase the CD44+/CD24lo stem cell pool, resulting in increased sphere forming capacity in vitro, as well as elevated tumorigenicity and metastasis in vivo." (PMID 34459003, 2021). "In breast cancer, the NONHSAT101069/miR-129-5p/Twist1 axis was shown to promote Epirubicin resistance." (PMID 33869020, 2021). "In breast cancer, the deposition of collagen activates LYN kinase to directly phosphorylate TWIST1 and drives tumour cell EMT and migration by increasing ECM stiffness." (PMID 34930901, 2021). "For example, the EMT–TFs Snail and Twist1 promote metastasis in various types of cancers including breast cancer, lung cancer, and HNSCC; however, an independent study revealed that Snail or Twist1 is dispensable for metastasis in pancreatic cancer." (PMID 32143517, 2020). "All these results revealed that the inhibition effect of TFPI2 on breast cancer progression was reversed by TWIST1 over-expression, which confirmed the effect of TFPI2/TWIST1 axis on regulation of breast cancer progression." (PMID 32248791, 2020). "In breast cancer, the activation of EMT-inducing transcription factors, such as Slug, ZEB, Twist1, and TGF-β, induces EMT and promotes metastasis in breast cancer." (PMID 32754303, 2020). "The downregulation of the expression of EMT transcription factors Snail‐1, Snail‐2, Twist‐1, Zeb‐1, and MMP‐3 in IL‐22−/−PyMT tumors suggests that IL‐22 mediates invasion through the EMT pathway in breast cancer." (PMID 31725949, 2020). "Twist1 is upregulated in many types of cancer such as HCC, gastric cancer, breast cancer, prostate cancer, and lung cancer." (PMID 33381597, 2020). "TWIST1 is widely known as EMT-inducing transcription factor that promote cell migration and invasion, and is also shown to be prognostic biomarker for breast cancer." (PMID 32248791, 2020). "It has been observed that a mitogen-activated protein kinase (MAPK) phosphorylates the Twist-related protein 1 (TWIST1) on N-terminal Ser68, and stabilizes it to enhance cancer cell migration, invasion, and metastasis in breast cancer cells." (PMID 32397221, 2020). "TGF-β-ID1 signaling inhibits Twist1 and promotes metastatic colonization via MET in breast cancer, whereas ID1 induces MET in metastatic cells during lung colonization." (PMID 33170151, 2020). "Mechanistically, Twist1 recruits the nucleosome remodeling deacetylase (NuRD) complex which in turn represses the E-cadherin expression and induces EMT in breast cancer." (PMID 32685483, 2020). "The present study showed that TWIST1 was negatively correlated with TFPI2 in breast cancer patients, and the inhibition ability of TFPI2 on breast cancer progression was reversed by over-expression of TWIST1." (PMID 32248791, 2020).
breast carcinoma (continued). "In another study, miR-33b expression was shown to be inversely correlated with the presence of lymph node metastases in breast cancer patients and to inhibit stemness, migration and invasion potential in vitro by targeting HMGA2, SALL4 and Twist1." (PMID 31906022, 2019). "In conclusion, detection of TWIST1 overexpression and stem-cell (CD24, CD44, ALDH1) transcripts in the EpCAM+ CTC fraction provides prognostic information in early stage breast cancer patients." (PMID 31261917, 2019). "Doxorubicin (1 μM) was found to significantly stimulate the expression of PLG (plasminogen, downregulated by Twist1 inhibitors; ANGPT2 (involved in breast cancer metastasis in brain); IGF-1 (a stimulator of TWIST1) and GLI1 (activated upon TWIST1 activation)." (PMID 31331001, 2019). "The aim of the current study was to evaluate the prognostic significance of TWIST1, CD24, CD44, and ALDH1 mRNA quantification in EpCAM-positive circulating tumor cells from early stage breast cancer patients with a long follow-up." (PMID 31261917, 2019). "In vivo Twist1 protein expression was higher in both TIS21-KO mice and the lymph node-positive human breast cancers." (PMID 31138781, 2019). "Twist1 could induce ECM remodeling by activating cancer-associated fibroblast to synthesize and secret high levels of ECM proteins, such as MMP2, which was proved to be related to tumor formation, metastasis, and responsible for high mortality breast and poor prognosis in breast cancer patients." (PMID 30819235, 2019). "We hereby presented the new role of BTG2/TIS21 gene as an inhibitor of Twist1 translation in the TNBC cells and the phenomenon was evidenced in tissues of the BTG2/TIS21-KO mice and human breast cancers." (PMID 31138781, 2019). "In this study we evaluated for the first time the prognostic significance of TWIST1, CD24, CD44, and ALDH1 transcript quantification in EpCAM-positive circulating tumor cells isolated from peripheral blood of early stage breast cancer patients." (PMID 31261917, 2019). "Western blotting results also confirm the elevated expression of E‐cadherin and the reduction in Vimentin and Twist1 expression, which is similar to the effect of MYOF in breast cancer cells." (PMID 29164766, 2018). "Many of the genes regulated have previously been shown to correlate with aggressiveness of breast cancer such as CD24, SOX2, Slug, Twist1, CD-133, N-Cadherin, E-Cadherin, FOXC2, ABCG2, c-Myc, IL8, IL6, and IKKβ (activating NF-κB signaling)." (PMID 29552303, 2018). "A recent meta‐analysis in metastatic breast cancer including 3218 patients has revealed that the individual or combined high expression levels of the EMT‐TFs, Twist1, Snail1, and Snail2, significantly correlated with poor prognosis." (PMID 28590039, 2017). "In epithelial breast cancer cells, TIMP1 induced TWIST1 expression, leading to E-cadherin downregulation and epithelial mesenchymal transition in a CD63-dependent manner." (PMID 28430130, 2017). "The metastatic process in breast cancer is related to the expression of the epithelial-to-mesenchymal transition transcription factors (EMT-TFs) SNAIL, SLUG, SIP1 and TWIST1." (PMID 28107418, 2017). "Pearson's correlation analysis run on 226 samples made up of 56 breast cancer cells showed that the FRK transcript levels negatively correlated with the transcript levels of VIM, CDH2, and TWIST1, with R-values of -0.28; -0.20; -0.25 respectively (P<0.001)." (PMID 29348886, 2017). "By binding to the putative promoter of miR-10b, Twist1 can induce the expression of miR-10b which inhibits the translation of homeobox D10, leading to the induction of pro-metastatic gene RHOC in breast cancer cells and a mouse model." (PMID 28099910, 2017). "In the present study, we found that the improved survival after breast cancer with high RPA was greatest among patients with methylated APC, CCND2, HIN1, and TWIST1 promoters." (PMID 28222775, 2017).
breast carcinoma (continued). "We characterized NF-κB/p65 as a transcriptional regulator of the main EMT-inducing factors related to metastatic progression in breast cancer: SLUG, SIP1 and TWIST1." (PMID 28107418, 2017). "Knockdown of TRIM28 resulted in TWIST1 downregulation with concurrent upregulation of E-CADHERIN and downregulation of N-CADHERIN that consequently inhibited breast cancer cell migration and invasion in vitro." (PMID 28851455, 2017). "First, we analyzed expression of TWIST1, E-cadherin and p-ERK that are involved in EMT and metastasis of breast cancer." (PMID 28430585, 2017). "This is the first study to demonstrate that miR-151-3p directly regulates TWIST1 expression by targeting the TWIST1 3’UTR and thus represses the migration and invasion of human breast cancer cells by enhancing E-cadherin expression." (PMID 27930738, 2016). "Here we report that a TRIM28-TWIST1-EMT axis exists in breast cancer cells and TRIM28 promotes breast cancer metastasis by stabilizing TWIST1 and subsequently enhancing EMT." (PMID 27412325, 2016). "In conclusion, these results suggest that miR-151-3p directly regulates TWIST1 expression by targeting the TWIST1 3’UTR and thus repressing the migration and invasion of human breast cancer cells by enhancing E-cadherin expression." (PMID 27930738, 2016). "Alternatively, TGFβ induces the transcription factor ATF3, in order to transactivate Snail1, Snail2 and Twist1, promoting EMT in Ras-transformed breast cancer cells." (PMID 27367735, 2016). "Given the fact that TWIST1 is an important regulator of cell migration and invasion and its expression is highly correlated with the levels of TRIM28 in breast cancers, we decided to explore the effects of TRIM28 on cell migration and invasion." (PMID 27412325, 2016). "TWIST1 is known as a critical regulator of EMT and is a transcriptional repressor of E-cadherin gene expression in breast cancer." (PMID 27930738, 2016). "ARTN activation of AKT was previously demonstrated to promote the expression of BCL-2 and TWIST1 resulting in enhanced oncogenicity and an increased CSC population in breast cancer." (PMID 26675549, 2016). "A recent study also showed that over-expression of CT45A1, CT antigen in breast cancer cells selectively enhanced the expression of pro-EMT gene, including TWIST1, ALDH1A1." (PMID 27658496, 2016). "miR-33b can inhibit the self-renewal of breast cancer cells and their migration and invasion capabilities by targeting HMGA2, SALL4 and Twist1." (PMID 25919570, 2015). "This suggests that SATB1 overexpression increases the size of the stem cell pool, and also activates Notch signaling pathways, increasing the expression levels of Snail1 and Twist1, which drive EMT in breast cancer cells." (PMID 25586771, 2015). "The mechanism through which miR-33b inhibits the stemness, migration and invasion of breast cancer cells is by targeting HMGA2, SALL4 and Twist1." (PMID 25919570, 2015). "Previous studies have also shown that the inhibition of miR-10b expression in breast cancer cells induced by WISP-2 is critical for the anti-invasive function of this gene and is mediated via the inhibition of the JNK-HIF-1α-TWIST1 signaling cascades." (PMID 25435966, 2015). "As another illustration of this concept, AKT-mediated phosphorylation of the EMT transcription factor TWIST1 leads to transcriptional activation of the TGFβ2 promoter and activated TGFβ signaling promoting EMT and breast cancer metastasis." (PMID 26204939, 2015). "Strikingly, our present data show that BRMS1 downregulates not only TWIST1 but also Snail expression, thereby attenuating TGF-β1-induced breast cancer cell EMT and invasion." (PMID 26520789, 2015). "Interestingly, Twist1 can promote the expression of miR-10b by directly binding to the promoter of miR-10b, which indicates that miR-10b may affect the invasion, intravasation, circulation, extravasation and metastatic colonization of breast cancer cells." (PMID 26146543, 2015).
breast carcinoma (continued). "Second, silencing either Snail or TWIST1 expression recovered TGF-β1-induced E-cadherin expression and breast cancer cell EMT." (PMID 26520789, 2015). "Several studies evaluated expression of EMT transcription factors (SNAIL, SLUG, ZEB1, ZEB2, TWIST1, and TWIST2) in breast cancer tissue sections." (PMID 26194471, 2015). "Overexpression of transcription factors (TF), including TWIST1, SNAIL1, SLUG, ZEB1 and/or FOXC1,2, can induce EMT in mammary epithelial cells and/or breast cancer cells as well." (PMID 26194471, 2015). "Collectively, these data indicate that miR-33b can inhibit breast cancer stem-like cell self-renewal by targeting HMGA2, SALL4 and Twist1." (PMID 25919570, 2015). "In the present study, we provide evidence that in addition to TWIST1, BRMS1 attenuates breast cancer cell invasion through downregulating Snail expression." (PMID 26520789, 2015). "It has been suggested that Snail1 activity is required for EMT initiation, whereas Twist1 serves a role in the maintenance of EMT in mammary epithelial and breast cancer cells." (PMID 25586771, 2015). "The ectopic expression of miR-33b downregulated the expression of ADAM9, HMGA2, LDHA, SALL4, SNAI2 and Twist1 by more than 30% but had minimal effects on HIF-1α, RAC1, Yes1 and ZEB1 in these two breast cancer cell lines." (PMID 25919570, 2015). "In the present study, we observed that BRMS1 efficiently inhibited TGF-β1-induced breast cancer cell EMT and invasiveness by downregulating not only TWIST1 but also Snail expression." (PMID 26520789, 2015). "We therefore analyzed the expression of mesenchymal markers connected with EMT activation (VIM, TWIST1, SNAI1 and SNAI2) in PT, CTCs-EBF and LNM of breast cancer patients." (PMID 24217115, 2013). "It is also consistent with the observed rapid and repeated appearance of multifocal breast carcinomas in WAP-Cre;K-rasG12D;Twist1 mice." (PMID 22654675, 2012). "Here we describe a unique property of the TWIST1 WR domain in mediating IL8 production and breast cancer cell invasion." (PMID 22891766, 2012). "TWIST1 signalling has been reported to promote VEGF-A expression in mammary carcinoma cells and we have previously demonstrated that ARTN increased TWIST1 expression to modulate ARTN stimulated oncogenicity." (PMID 23185544, 2012). "To further confirm the correlation of expression between TWIST1 and ARTN in mammary carcinoma, we compared the relationship by Spearman's rank correlation coefficient and found a significant positive value (Spearman correlation: rs = 0.21, P = 0.03)." (PMID 22060274, 2011). "Indeed, similar to the previous studies conducted in clear-cell renal cell carcinoma and breast cancer cell lines, HIF-1α binding to the HRE of the TWIST1 proximal promoter was also inhibited by CpG methylations of the element as demonstrated by EMSA." (PMID 40764968, 2025). "Additionally, research conducted by Y Xu and his team revealed that Twist1 can suppress FOXA1 expression, thereby enhancing the invasive and metastatic properties of breast cancer." (PMID 40003882, 2025). "Multiple EMT-inducing transcription factors, such as TWIST1, SNAIL1/2, and ZEB1/2, may be expressed to drive breast cancer cells to undergo EMT and produce increased invasion, metastasis, and resistance to therapies, including immunotherapy." (PMID 38893094, 2024). "Furthermore, PD-L1 (CD274) protein is expressed at low levels in ER+/HER2−/TWIST1− epithelial breast cancer cell lines, including MCF7, ZR-75-1, and T47D, while it is at high levels in ER−/HER2−/TWIST1+ TNBC cell lines, including MDA-MB-436, BT549 and SUM1315." (PMID 38893094, 2024). "The knockdown of TWIST1 or BRD8 or the blockade of PD-L1 activity can successfully reverse CD8+ T-cell exhaustion and reinvigorate CD8+ T cells, leading them to inhibit the growth of breast cancer cells." (PMID 38893094, 2024).